CDK4 (cyclin dependent kinase 4)
Diseases named in the same sentence as CDK4 in open-access papers (continued):
Sharing a sentence is not in itself a finding about the gene and the disease.
breast cancer (continued). "The ORR and DCR of patients with HR + breast cancer (12.5% and 62.5%, respectively) were comparable to those of other CDK4/6 inhibitors." (PMID 40586764, 2025). "CDK4/6 inhibitors combined with aromatase inhibitors (CDK4/6 inhibitor + AI) demonstrate efficacy in metastatic HR+ breast cancer, with real-world evidence showing improved overall and progression-free survival compared to AI alone." (PMID 41373749, 2025). "This is expected given fewer patients from Japan had been treated with prior endocrine therapy or CDK4/6 inhibitors for advanced breast cancer compared with the global CAPItello-291 population; fewer patients from Japan had also received prior chemotherapy." (PMID 39379782, 2025). "While there is improvement in PFS and OS with the combination of CDK4/6 inhibitors with endocrine therapy in breast cancer patients, all the patients ultimately progress." (PMID 40075623, 2025). "Several lines of evidence have proposed the clinical benefits of CDK4/6 inhibitors in advanced breast cancer." (PMID 40740245, 2025). "Inhibiting kinase activity, thereby blocking cell cycle progression from G1 to S phase and preventing tumor cell proliferation In HR+ breast cancer cells, growth signals such as estrogen activate cyclin D, which binds to CDK4/6 to form a complex." (PMID 41244784, 2025). "Palbociclib, a CDK4/6 inhibitor, has demonstrated significant therapeutic benefit in HR+ breast cancer; however, acquired resistance to CDK4/6 inhibition has been widely reported in both clinical and preclinical studies." (PMID 40631077, 2025). "CDK4/6 inhibitor therapies used in the treatment of breast cancer have significantly improved therapeutic outcomes." (PMID 40422590, 2025). "The CAPItello‐291 (NCT04305496) study is a phase III clinical trial focusing on patients with HR‐positive/HER2‐negative advanced breast cancer previously treated with CDK4/6i." (PMID 40206206, 2025). "We found that TMEM45A is highly expressed in cells resistant to CDK4/6i, promoting the invasive ability of breast cancer cells." (PMID 39910045, 2025). "The current first‐line treatment for patients with HR+/HER2− advanced breast cancer (ABC) involves the use of cyclin‐dependent kinase 4/6 (CDK4/6) inhibitors in combination with ET." (PMID 41322031, 2025). "For instance, palbociclib is a chemotherapeutic agent and the first CDK4 inhibitor approved for breast cancer." (PMID 40293950, 2025). "This is exemplified by PIK3CA mutations in 30%–40% of HR+ breast cancers, driving constitutive PI3K pathway activation and conferring dual resistance to CDK4/6 inhibitors and endocrine therapies." (PMID 40421216, 2025). "Inhibitors targeting CDK4/6, as palbociclib, ribociclib, and abemaciclib offer both hope and challenges for the treatment of breast cancer." (PMID 40717978, 2025). "Cyclin-dependent kinase 4 and 6 (CDK4/6) inhibitors have transformed the treatment landscape for patients with hormone receptor-positive (HR+)/HER2-negative (HER2−) breast cancer." (PMID 40244189, 2025). "For example, based on the important role of cyclin D1 overexpression in enhancing breast cancer cell proliferation, various cell cycle inhibitors targeting CDK4 have been developed to treat breast cancer." (PMID 41161384, 2025). "Studies have further confirmed that CDK4/6 selective inhibitors and estrogen receptor (ER) antagonists exhibit significant synergistic effects in inhibiting the proliferation of ER-positive breast cancer cells." (PMID 41438984, 2025). "It was also recently demonstrated that the p27/CDK4/Cyclin D ternary complex is insensitive to the CDK4-targeting drug palbociclib, suggesting that the protein can participate in determining breast cancer palbociclib resistance." (PMID 39936980, 2025). "Inhibitors of CDK4, including abemaciclib, have been employed in the management of breast cancer that is positive for hormone receptors." (PMID 40507905, 2025).
breast cancer (continued). "Aberrant activation of the CDK4/6-Rb axis is a common feature in various malignancies, including breast cancer, promoting unchecked cellular proliferation." (PMID 41148817, 2025). "This study provides new insights into the differential efficacy of CDK4/6 inhibitors in metastatic and locally advanced breast cancer, emphasizing the importance of personalized treatment strategies." (PMID 40244189, 2025). "In the HR+/HER2− relapsed breast cancer population, progressing after an AI plus CDK4/6i, samuraciclib plus fulvestrant was responsible for a 36% CBR." (PMID 40244377, 2025). "The addition of a cyclin-dependent kinase 4/6 (CDK4/6) inhibitor to endocrine therapy augments biological response in breast cancer." (PMID 40888443, 2025). "Multiple CDK4/6 inhibitors have been approved for the treatment of HR + /HER2- advanced breast cancer." (PMID 41259313, 2025). "Several studies are currently examining the efficacy of first‐line CDK4/6 inhibitors for metastatic breast cancer patients having aggressive visceral metastasis, in light of the improved outcomes brought by these inhibitors." (PMID 41339109, 2025). "The objective of this study was to assess the effectiveness and safety of CDK4/6 inhibitors in the treatment of hormone receptor-positive (HR+) breast cancer by using meta-analysis." (PMID 40104496, 2025). "Current guidelines recommend the combination of endocrine treatment (aromatase inhibitor or fulvestrant) and a cyclin-dependent kinase 4/6 inhibitor (CDK4/6i) as first-line treatment for advanced HR+/HER2− breast cancer." (PMID 41226406, 2025). "Wild type CRAF can control endocrine therapy by directly activating CDK4, and up to 8% in a cohort of metastatic breast cancers harbor genetic alterations in CRAF (e.g., amplification)." (PMID 41226361, 2025). "CDK4/6 inhibitors are integral to the treatment of HR+/HER2− breast cancers by targeting ER-mediated cyclin-dependent signaling." (PMID 40287441, 2025). "A previous meta-analysis showed promising results, demonstrating that the combination of CDK4/6i with endocrine therapy improved iDFS in patients with early-stage HR+/HER2− breast cancer compared with those who were treated with hormone therapy alone." (PMID 41228331, 2025). "In light of this mechanism, CDK4/6 inhibitors have emerged as potential therapeutic options for ER+ breast cancer." (PMID 40104496, 2025). "CDK4/6 inhibitors have emerged as promising therapeutic agents in HR-positive (HR+)/HER2-negative (HER2−) breast cancer." (PMID 39930131, 2025). "A major focus of their research was to exploit these PDXs to assess the resistance to CDK4/6 inhibitors (CDK4/6i), which are critical in managing advanced luminal breast cancers." (PMID 40145404, 2025). "In the MAINTAIN phase II trial, an HR+/HER2− relapsed breast cancer population progressing during ET plus CDK4/6i changed the ET (to fulvestrant or exemestane) and were randomly allocated to treatment with ribociclib or a placebo." (PMID 40244377, 2025). "Case presentation: We report a case of an Asian female with left breast cancer who underwent a modified radical mastectomy followed by adjuvant chemotherapy, RT, endocrine therapy, and CDK4/6i (abemaciclib) treatment." (PMID 40430137, 2025). "Abemaciclib is the first CDK4/6 inhibitor to achieve positive results in the adjuvant treatment of early breast cancer." (PMID 40002156, 2025). "Overall, 1966 patients were treated with CDK4/6 inhibitors, including 1780 patients with breast cancer." (PMID 40896464, 2025).
breast cancer (continued). "This study aimed to evaluate the comprehensive safety profile of CDK4/6 inhibitors in breast cancer treatment by analyzing real-world adverse event (AE) data and systematically reviewing clinical trial findings to provide evidence-based safety guidance." (PMID 41458615, 2025). "The TRINITI-1 trial evaluated the triplet regimen of ribociclib, everolimus, and exemestane in HR+/HER2− advanced breast cancer patients who had progressed on prior CDK4/6 inhibitor therapy." (PMID 41002573, 2025). "In the clinical trial known as VERITAC, ARV‐471 contributed to potent efficacy and manageable safety profiles in patients with locally advanced or metastatic ER+/HER2− breast cancer who had prior CDK4/6i therapy." (PMID 41357671, 2025). "A CDK4 specific inhibitor, atirmociclib, has successfully been shown to halt breast cancer growth with reduced effect on neutrophil levels." (PMID 40093074, 2025). "In early-stage breast cancer, the three CDK4/6 inhibitors with currently published results have inconsistent effects." (PMID 40002156, 2025). "Treatment with endocrine therapy (ET) in combination with CDK4/6 inhibitors has improved the outcome of patients with hormone receptor (HR)+/HER2- advanced breast cancer (ABC), but most patients eventually experience disease progression." (PMID 40565304, 2025). "The preferential efficacy of CDK4/6 inhibitors in HR+/HER2- breast cancer stems from this subtype’s unique molecular dependencies." (PMID 40421216, 2025). "In summary, CDK4/6 combined endocrine therapy is still the first choice for first-line endocrine therapy for endocrine-sensitive HR+ advanced breast cancer." (PMID 40104496, 2025). "Several in vivo studies have also demonstrated the effect of palbociclib on bone metastases and the efficacy of the RANK pathway and CDK4/6 inhibition in luminal breast cancer." (PMID 40005476, 2025). "Non-steroidal aromatase inhibitors, either alone or in combination with CDK4/6 inhibitors, are the first-line treatment options for human breast cancer (HR+/HER2−)." (PMID 40642276, 2025). "Among other therapeutic approaches, CDK4/6i has become one of the most important therapeutic advancements in breast cancer." (PMID 41228331, 2025). "Recently, a clinical investigation demonstrated an inverse correlation between CDK6 overexpression and PFS in ER+ breast cancer patients undergoing CDK4/6i therapy." (PMID 40244377, 2025). "Obesity‐related systemic inflammation is known to activate IGF and leptin signals that promote the growth of breast cancers and resistance to ET and CDK4/6i." (PMID 39686815, 2025). "Their positive effects on patient survival, quality of life, and favorable safety profiles have made CDK4/6 inhibitors a cornerstone of breast cancer treatment." (PMID 40142360, 2025). "HR+/HER2− breast cancer, which typically retains Rb function and activates the cyclin D–CDK4/6 pathway via estrogen signaling, has the highest sensitivity to CDK4/6 inhibition." (PMID 39930131, 2025). "Currently, there are two CDK4/6 inhibitors that have been approved globally for HR+/HER2- early breast cancer." (PMID 40002156, 2025). "Palbociclib is an oral cyclin‐dependent kinase 4 and 6 (CDK4/6) inhibitor that has been documented to slow breast cancer cell growth with estrogen receptors and can also work well with anti‐estrogen drugs." (PMID 41339109, 2025). "The last dual CDK4/6 inhibitor to be approved for breast cancer treatment, at least from the Chinese NMPA, was dalpiciclib." (PMID 39800748, 2025). "Our CRISPR screens identified JNK pathway loss, or potential tumour suppressive action, in the context of first-line combination endocrine and CDK4/6 inhibitor treatment for ER+ breast cancer." (PMID 40826108, 2025). "CDK4/6 inhibitors (CDK4/6i), such as palbociclib, have proven useful in the treatment of advanced ER + breast cancer; however, resistance to these therapies poses a significant challenge." (PMID 40650785, 2025).
breast cancer (continued). "Targeted therapy with CDK4/6 inhibitors in addition to endocrine therapy has been widely studied in early breast cancer." (PMID 40959380, 2025). "This suggests a potential connection between host body composition status and the sensitivity of breast cancer cells to ET and CDK4/6i." (PMID 39686815, 2025). "In advanced/metastatic breast cancer, CDK4/6 inhibitors (CDK4/6i) are approved in the UK for use in HR+ HER2- breast cancer, either in previously untreated patients or following endocrine therapy, in combination with fulvestrant or aromatase inhibitors." (PMID 41091336, 2025). "Even though the presented data focus on aBC, extending this approach to early breast cancer in future studies and routine care will be essential in light of recent trials and treatment guideline updates integrating CDK4/6 inhibitors into the adjuvant setting." (PMID 41534416, 2025). "In CDK4/6 inhibitor-resistant breast cancer cells, tumor growth shifts dependency from hormone receptor (HR) signaling to hyperactivated PI3K/AKT/mTOR cascades." (PMID 40421216, 2025). "In this report, we examined the potential efficacy of this novel strategy in vivo using a cell line xenograft model of endocrine and CDK4/6 inhibitor-resistant breast cancer." (PMID 40206590, 2025). "In this respect, several findings support the rationale of combining CAF-targeting strategies with the CDK4/6 inhibition, especially for ERα-positive breast cancer." (PMID 41388212, 2025). "[18F]FES PET can be employed as a predictive tool for treatment response in breast cancer patients with different types of therapy (i.e., endocrine therapy ± CDK4/6 inhibitor, neoadjuvant endocrine/chemotherapy)." (PMID 40427142, 2025). "This study assessed the feasibility and performance of a tumor-informed circulating tumor DNA (ctDNA) assay in metastatic HR+/HER2− breast cancer patients receiving endocrine and CDK4/6 inhibitor therapy." (PMID 40683861, 2025). "The rise of perioperative immunological therapies, new CDK4-specific inhibitors, and targeted endocrine treatments can lead to a notably favorable prognosis for many previously high-risk HR+/HER2- breast cancers." (PMID 40557948, 2025). "In HR+/HER2-advanced breast cancer, the medical community has been exploring new therapeutic options for patients who develop resistance after CDK4/6 inhibitors combined with endocrine therapy." (PMID 39917165, 2025). "The synergistic inhibition of both ER signalling and CDK4/6 has proven highly effective in advanced breast cancer, forming the rational basis for their combined use." (PMID 41440236, 2025). "We examined pJNKT183/Y185 activity by IHC in a second cohort of metastatic ER+ breast cancer patients treated with combined endocrine therapy and CDK4/6 inhibition." (PMID 40826108, 2025). "Given the role of cyclin D in activating CDK4/6, preclinical studies of breast cancer cell lines have revealed elevated levels of cyclin D proteins in cells sensitive to palbociclib." (PMID 39930131, 2025). "In our study, we focused on analyzing a group of patients diagnosed with HR+/HER2- breast cancer and their response to different CDK4/6 inhibitors." (PMID 40104496, 2025). "Transcriptomic profiling of palbociclib-resistant MCF-7 cells reveals upregulated autophagy-related genes and increased autophagosome formation, underscoring ER+ breast cancer’s reliance on autophagy to evade CDK4/6 blockade." (PMID 40421216, 2025). "The MONARCH 3, MONALEESA-2 and PALOMA-2 studies represent pivotal phase 3 studies establishing the role of CDK4/6 inhibitors in the first-line treatment of HR+/HER2− advanced breast cancer." (PMID 40136365, 2025).
breast cancer (continued). "While CDK4/6 inhibitors have shown clear benefits in breast cancer in a range of clinical circumstances as detailed above, their use in prostate cancer is not yet established." (PMID 40075623, 2025). "Here, we have identified inactivation of JNK signalling, specifically loss of the JNK kinase MAP2K7, as a major determinant of insensitivity to combined endocrine therapy and CDK4/6 inhibition in ER+ breast cancer." (PMID 40826108, 2025). "Our study employed an unbiased whole-genome approach to demonstrate that the JNK signalling cascade plays an important role in driving insensitivity to combination endocrine therapy and CDK4/6 inhibition in ER+ breast cancer." (PMID 40826108, 2025). "The gene amplification in FGFR1 has been shown to confer resistance to CDK4/6 inhibitor + letrozole and leads to a poor prognosis in patients with ER+ breast cancer." (PMID 40227585, 2025). "Data collected from several clinical studies testing the effectiveness of CDK4/6 inhibitors used in combination with ICIs are quite controversial, especially for breast cancer." (PMID 41388212, 2025). "In breast cancer patients with HR+ tumors, the activation of the CDK4/6 pathway has been identified as a contributing factor to resistance against endocrine therapy." (PMID 40740245, 2025). "A key dysregulation in breast cancer involves the overactivation of cyclin-dependent kinases 4 and 6 (CDK4/6)." (PMID 39605351, 2025). "To better understand the clinical benefits of CDK4/6 inhibitors in patients with advanced breast cancer who are HR+ and HER2-, we conducted a meta-analysis comparing pooled data on the use of CDK4/6 inhibitors versus placebo from the most recent reports." (PMID 40740245, 2025). "An additional phase III study evaluating gedatolisib combined with palbociclib and fulvestrant in patients with HR+/HER2− advanced breast cancer that progressed after treatment with a CDK4/6 inhibitor and an aromatase inhibitor is also underway (NCT05501886)." (PMID 40711480, 2025). "Elevated spliced form of X‐box–binding protein 1 (XBP1) correlates with unfavorable responses to endocrine therapy plus CDK4/6 inhibitors in HR+/HER2− advanced breast cancer." (PMID 40940685, 2025). "Despite the positive results of ADCs in advanced HR+/HER2− breast cancer, endocrine therapy plus CDK4/6 inhibition remains the standard first-line approach." (PMID 41562776, 2025). "Recent reviews and meta-analyses also highlight the long-term safety and evolving efficacy of CDK4/6 inhibitors in advanced breast cancer management, reinforcing their transformative potential in clinical oncology." (PMID 40109794, 2025). "These APOBEC3-driven mutations have been independently linked to shorter PFS in patients receiving a combination of anti-estrogen therapy and CDK4/6is (CDK4/6is) for HR+ relapsed breast cancer." (PMID 40244377, 2025). "After the success of CDK4/6i as a therapeutic option for HR+/HER2– breast cancer, the focus naturally shifted toward HER2+ breast cancer." (PMID 40940886, 2025). "Emerging evidence highlights the critical role of STAT3 signaling in mediating CDK4/6 inhibitors resistance in several cancers including breast cancer." (PMID 40303916, 2025). "Accordingly, specific CDK7is, like samuraciclib, have shown therapeutic efficacy in HR+/HER2− advanced breast cancer populations resistant to CDK4/6is." (PMID 40244377, 2025). "Overall, this is the first pooled analysis to demonstrate the OS and PFS benefits of CDK4/6 inhibitors in elderly patients (age ≥65 years) with advanced HR+/HER-2 metastatic or advanced breast cancer." (PMID 40440494, 2025). "A breakthrough came with the development of selective CDK4/6 inhibitors, which have demonstrated efficacy in human luminal/estrogen receptor-positive cancer cells, suggesting their potential utility in breast cancer treatment." (PMID 39930131, 2025).